BECN1 (beclin 1)
Diseases named in the same sentence as BECN1 in open-access papers (continued):
Sharing a sentence is not in itself a finding about the gene and the disease.
endotoxemia (continued). "We previously showed that activation of autophagy initiator Beclin-1 provided a benefit of cardiac protection during endotoxemia." (PMID 34211859, 2021). "In the hearts of animals challenged by endotoxemia, Beclin-1 stimulates a striking difference in the spectrum of mitochondria-localized mitophagy factors, indicating a differential regulation of mitophagy pathways." (PMID 30744190, 2019). "As dysfunctional mitochondria can be segregated and eliminated through autophagy, a process termed mitophagy, Beclin-1-mediated quality control of cardiac mitochondria during endotoxemia is expected to be a product of an upregulated mitophagy." (PMID 30744190, 2019). "In the model of LPS-induced endotoxemia, increasing Beclin-1-dependent autophagy improved cardiac outcomes and attenuated the production of cytokines." (PMID 30744190, 2019). "For example, a newly developed cell permeable peptide, TB peptide that activates Beclin-1, showed therapeutic promise in a mouse model of LPS-induced endotoxemia." (PMID 30744190, 2019). "Genetic mouse models with altered expression of Beclin-1 were applied to determine the role of cardiac autophagy in response to LPS-induced endotoxemia." (PMID 30744190, 2019). "This study was to determine whether endotoxemia rearranges MAMs in the heart, and whether Beclin‐1 regulates this process." (PMID 33733054, 2021). "The data also suggest that pharmacological approaches that activate Beclin‐1 signaling may hold a therapeutic potential to preserve MAM properties during endotoxemia." (PMID 33733054, 2021). "In a mouse model of endotoxemia, we obtained new findings showing that septic challenge by LPS incites losses in myocardial MAMs, and this damage was alleviated by the targeted activation of Beclin‐1 either genetically or pharmacologically." (PMID 33733054, 2021). "We discovered that enhancing autophagy via the specific activation of Beclin-1, a universally expressed autophagy initiation factor, protects mitochondria, reduces mitochondrial DAMPs, and alleviates inflammation in the heart during endotoxemia." (PMID 34211859, 2021). "We also obtained data suggesting a new function for Beclin‐1 in supporting the properties of MAMs, either by inducing the new formation of MAMs or by defending them from degradation, which thus improves cardiac mitochondria and protects the heart in response to endotoxemia." (PMID 33733054, 2021). "Furthermore, the pharmacological activation of Beclin‐1 by TB‐peptide showed a beneficial effect by preserving MAM mass and function in those mice undergoing endotoxemia." (PMID 33733054, 2021). "Data presented here obtained both in vitro and in vivo suggest that Beclin‐1 has a new function to maintain proper MAMs in the heart, and a specific activation of Beclin‐1 signaling can attenuate an LPS‐induced decline in MAM quality and quantity during endotoxemia." (PMID 33733054, 2021).
gastric adenocarcinoma (6 papers, 2014 to 2021). "SKP2 expression was positively correlated with the tumoral FOXP3 overexpression (P < .0001), Beclin-1 expression (P < .0001), and Treg infiltration (P = .031) in gastric adenocarcinoma." (PMID 34414959, 2021). "Especially, SKP2 expression was positively correlated with Beclin-1 expression in gastric adenocarcinoma." (PMID 34414959, 2021). "A positive Beclin-1 expression was observed in 59.3% (108/182) of the gastric adenocarcinoma samples." (PMID 34414959, 2021). "Results demonstrated that Beclin 1 is highly expressed in low grade differentiated gastric adenocarcinoma cells, compared with normal mucosal tissues." (PMID 24527069, 2014). "A significant increase of Beclin 1 was observed in patients with low grade differentiated gastric adenocarcinoma." (PMID 24527069, 2014). "When gastric adenocarcinoma cells were dual-labeled with these two antibodies, Bcl-2 immunoreactivity colocalized with Beclin 1 immunoreactivity in poorly differentiated human gastric adenocarcinoma." (PMID 24527069, 2014). "With regard to gastric adenocarcinoma, double immunostaining analyses of the present study demonstrated colocalization of Beclin 1 and Bcl-2-positive immunoreactivity in human gastric adenocarcinoma." (PMID 24527069, 2014). "Correlation among SKP2, tumoral FOXP3, Beclin-1, and Tregs in 182 gastric adenocarcinomas." (PMID 34414959, 2021). "In our previous study, we concluded that the expression of the autophagy-related protein, Beclin-1, was associated with tumor FOXP3 expression and Tregs in gastric adenocarcinoma and that Beclin-1 expression acts as a favorable prognostic factor in gastric adenocarcinoma." (PMID 34414959, 2021). "Notably, confocal laser microscope data indicated co-expression of Bcl-2 and Beclin 1 in poorly differentiated human gastric adenocarcinoma." (PMID 24527069, 2014). "Although variable loss expression of Beclin 1 has been observed in several types of human tumors, the relationship between Beclin 1 expression and gastric adenocarcinoma patient survival remains unclear." (PMID 24527069, 2014). "Furthermore, we hypothesize that increased Bcl-2/Beclin 1 signaling in human gastric adenocarcinoma may contribute to the interplay of apoptotic and autophagic events." (PMID 24527069, 2014). "In the context of the present study, we hypothesize that Bcl-2/Beclin 1 signaling may be a critical regulator of the biological effects of gastric adenocarcinoma and may be a key signaling element for the autophagic process, reflecting the prognostic result of patients." (PMID 24527069, 2014). "Our study showed a complex interrelationship between SKP2 and Beclin-1 and FOXP3 expression in gastric adenocarcinoma." (PMID 34414959, 2021). "Our study showed a complex interrelationship among SKP2, Beclin-1, and FOXP3 expression (in the tumor cells and Tregs) in gastric adenocarcinoma." (PMID 34414959, 2021). "In the present study, the expression of SKP2 and its relationship with Beclin-1 and FOXP3 expression in gastric adenocarcinoma were investigated." (PMID 34414959, 2021). "In conclusion, the antioncogenic effect of Beclin-1 and FOXP3 expression in gastric adenocarcinoma is corresponding to SKP2 expression." (PMID 34414959, 2021). "The antioncogenic effect of Beclin-1 and FOXP3 expression in gastric adenocarcinoma is related to SKP2 expression." (PMID 34414959, 2021). "Moreover, it increases the formation of autophagosomes and controls proteins (Vps34, beclin 1, LC3-I, LC3-II, and p62) that induce autophagy in a gastric adenocarcinoma cell line." (PMID 32775437, 2020).
head and neck squamous cell carcinoma (6 papers, 2014 to 2025). A squamous cell carcinoma that arises from any of the following anatomic sites: lip and oral cavity, nasal cavity, paranasal sinuses, pharynx, larynx, and salivary glands. "MiR-630 was also found to be upregulated in head and neck squamous cell carcinoma after cisplatin treatment and can modulate the protein expression of ATG5, ATG6/BECN1, ATG10, ATG12, ATG16L1 and UVRAG." (PMID 24621930, 2014). "However, in head and neck squamous cell carcinoma Ca27 cells, activation of NF-κB p65 upregulated the expression of LC3-II and Beclin-1." (PMID 33427556, 2021).
Hepatitis (6 papers, 2012 to 2019). Inflammation of the liver. "In this study, we found that LC3-II and Beclin-1 are inhibited by H2S preconditioning during I/R-induced hepatitis in vitro and in vivo." (PMID 24966472, 2014). "The expression of BECN1 mRNA in the hepatitis tissue was significantly higher than that of the cirrhotic and normal tissues (P<0.05; χ2=8.30 and 5.65, respectively)." (PMID 23833647, 2013). "The expression of the BECN1 protein in the hepatitis tissue was significantly higher than that of the cirrhotic and normal tissues (P<0.05; χ2=4.44 and 4.12, respectively)." (PMID 23833647, 2013). "The present results demonstrated that the expression of BECN1 mRNA and protein were increased in hepatitis and HCC tissues." (PMID 23833647, 2013). "The expression of the BECN1 protein in the hepatitis tissue was significantly high compared with that of the cirrhotic and normal tissues." (PMID 23833647, 2013). "The expression of BECN1 protein in hepatitis tissue was significantly higher than that of cirrhotic and normal tissues, and the BECN1 protein expression was positively correlated with the NF-κBp65 protein expression in the HCC tissue." (PMID 23833647, 2013). "As autophagy may be involved in either cell death or survival, depending on the cellular context, the increased expression of BECN1 in the hepatitis and HCC tissues may have implications for its unknown biological role." (PMID 23833647, 2013). "The expression of the BECN1 mRNA in the cancer tissue was significantly high compared with that of the cirrhotic and normal tissues, and the expression of the BECN1 mRNA in the hepatitis tissue was significantly higher than that of the cirrhotic and normal tissues." (PMID 23833647, 2013). "To evaluate the effects of NAC on autophagy in ConA-induced hepatitis, we measured the levels of LC3II and Beclin 1 by real-time PCR and western blotting." (PMID 25821351, 2015). "The positive expression rates of BECN1 mRNA in the HCC, cirrhotic, hepatitis and normal tissues were 68.00, 23.33, 60.00 and 10.00%, respectively (P<0.05; χ2=22.61)." (PMID 23833647, 2013). "The expression level of the BECN1 protein in the HCC tissue was significantly high compared with that in the cirrhotic, hepatitis and normal tissues." (PMID 23833647, 2013). "The expression of the BECN1 protein in the HCC tissue was significantly higher than that of the cirrhotic, hepatitis and normal tissues (P<0.05; χ2=20.39, 5.31 and 14.42, respectively)." (PMID 23833647, 2013). "The expression rates of BECN1 protein in the HCC, cirrhotic, hepatitis and normal tissues were 78.00, 26.67, 53.33 and 10.00%, respectively (P<0.05; χ2=28.34)." (PMID 23833647, 2013). "The expression of the BECN1 and NF-κBp65 proteins in the HCC tissue was significantly higher than that of the cirrhotic, hepatitis and normal tissues." (PMID 23833647, 2013).
HIV-1 infection (6 papers, 2012 to 2021). The type species of lentivirus and the etiologic agent of acquired immunodeficiency syndrome (AIDS). "HIV-1 infection has been shown to induce autophagosome formation and increase protein expression of Beclin-1 and LC3 in Jurkat cells and CD4+ T cells." (PMID 28684681, 2017). "Similarly, treatment with a Tat-Beclin 1 peptide also induced autophagy and had a protective effect against HIV-1 infection of human monocyte-derived macrophages." (PMID 33669846, 2021). "In macrophages, the interaction of toll-like receptor 8 (TLR8) and HIV-1 induces autophagy by Beclin 1-dependent dephosphorylation of transcription factor EB (TFEB) and subsequently its nuclear translocation during the initial stages of HIV-1 infection." (PMID 33669846, 2021). "Our group has reported that HIV-1 infection induces autophagy in microglia by increasing the conversion of LC3I to LC3II and increasing expression of Beclin-1 and ATG5 proteins." (PMID 28684681, 2017). "We next tested whether priming with HIV-1 CA P90A could attenuate WT HIV-1 infection in ULK1 and BECN1 knockout THP-1 cells." (PMID 33052966, 2020). "However, this notion is somewhat unsettled because another group has reported that autophagy is induced by HIV-1 infection of CD4+ T cells, as shown by increased levels of Beclin-1 and LC3." (PMID 23110561, 2012).
kidney damage (6 papers, 2019 to 2024). "Our data clearly indicate that heterozygous deletion of Becn1 sensitized mice for cisplatin nephrotoxicity and subsequent nephropathy." (PMID 38473806, 2024). "On the contrary, Br-MSCs + EXO, EXOs, and Br-MSC-treated groups showed more significant upregulation in the mean value of renal Beclin-1 either gene or protein expression than the nephropathy and CM-treated groups, harmoniously." (PMID 37631363, 2023). "However, in the serum, the rise in urea level was accompanied by the increase in Beclin-1, which may lead to aggravation of the kidney damage." (PMID 32047576, 2020). "However, the rise of creatinine and urea levels was accompanied by the increase in Beclin-1 expression, which may lead to the aggravation of kidney damage." (PMID 32047576, 2020).
schizophrenia (6 papers, 2019 to 2025). A major psychotic disorder characterized by abnormalities in the perception or expression of reality. "We also observed abnormalities in the autophagy pathway, affecting brain homeostasis, via downregulation of the autophagy inducer BECN1 in both brain patient brain tissue and brain samples of Adnp deficient mice as well as in post-mortem schizophrenia brains." (PMID 38637827, 2024). "Low beclin-1 hippocampal levels have also been involved in the pathogenesis of schizophrenia, as the consequent downregulated autophagy causes neuronal cell death to rise." (PMID 37761179, 2023). "Taking into account that prenatal exposure to BP-3 caused substantial reduction of BECLIN-1, we suggest that BP-3 may increase the risk of schizophrenia since in brains of schizophrenia patients autophagy is impaired, particularly BECLIN-1 expression level is decreased by 40%." (PMID 30402708, 2019). "The reduced expression of BECN1 in the hippocampus of schizophrenia models correlated with impaired autophagy initiation and synaptic dysfunction." (PMID 40650013, 2025). "Given that BECN1 is essential for initiating autophagy, its decreased expression may hinder the autophagic process in hippocampal neurons, limiting their ability to degrade damaged cellular components and contributing to neuronal dysfunction in schizophrenia." (PMID 40362522, 2025). "The researchers demonstrated a significant reduction in mRNA levels of Beclin 1 (BECN1), a key autophagy-related protein, in the hippocampi of patients with schizophrenia." (PMID 40362522, 2025).
squamous cell carcinoma (6 papers, 2013 to 2022). A carcinoma arising from squamous epithelial cells. "For this reason, the objective of this study was to evaluate, through immunohistochemical techniques, the prognostic role of the expression of the Beclin-1 autophagy marker in patients with squamous cell carcinoma of the oral cavity." (PMID 34769649, 2021). "Our RT-PCR assays showed that the mean mRNA transcript levels of beclin-1 were 0.016±0.004 in hypopharyngeal squamous cell carcinoma tissues and 0.024±0.005 in the adjacent normal tissues (P<0.0001)." (PMID 23935917, 2013). "Similarly, the protein level of beclin-1 was markedly lower in the hypopharyngeal squamous cell carcinoma tissues (0.308±0.031) than in paired normal tissue (0.569±0.068) (P=0.02)." (PMID 23935917, 2013). "(A) Positive expression of beclin-1 in hypopharyngeal squamous cell carcinoma cells." (PMID 23935917, 2013). "We found a sustained increase in Bcl-2, Beclin-1, ATG5,LC-3 and p-AktSer473 associated with decreased expression of Bax and cleaved caspase-3 during progression of normal epithelium through hyperplasia, dysplasia and well-differentiated squamous cell carcinoma of the hamster buccal pouch." (PMID 30352996, 2018). "A positive correlation was observed between the mRNA transcript levels of beclin-1 and LC3 in hypopharyngeal squamous cell carcinoma tissues (r=0.51, P<0.0001; 95%CI: 0.273 to 0.689)." (PMID 23935917, 2013). "In the present study, we revealed for the first time that both beclin-1 and LC3-II are significantly downregulated in hypopharyngeal squamous cell carcinoma tissues compared to adjacent normal mucosal epithelium tissues." (PMID 23935917, 2013). "We examined the expression of beclin-1 and LC3 in hypopharyngeal squamous cell carcinoma tissues by immunohistochemistry." (PMID 23935917, 2013). "We analyzed whether beclin-1 and LC3 expression in hypopharyngeal squamous cell carcinoma tissues correlated with patient clinicopathologic characteristics." (PMID 23935917, 2013). "In this study, we found lower expression of beclin-1 in hypopharyngeal squamous cell carcinoma tissues vs. adjacent non-cancerous tissues at both the mRNA and protein levels." (PMID 23935917, 2013). "(E) Negative expression of beclin-1 in hypopharyngeal squamous cell carcinoma cells." (PMID 23935917, 2013). "Beclin-1 and LC3 were mainly located in the cytoplasm or on the cell membrane in both hypopharyngeal squamous cell carcinoma cells and squamous epithelial cells in adjacent non-cancerous tissue with occasional expression of LC3 in the nuclei." (PMID 23935917, 2013).
uveal melanoma (6 papers, 2020 to 2024). A melanoma derived from melanocytes of the uveal tract. "There is also evidence that Beclin-1 has a positive prognostic role in uveal melanoma, with higher levels of immunohistochemistry associated with a low risk of metastasis and better overall survival." (PMID 38467935, 2024). "The level of Beclin-1 expression on primary uveal melanoma correlated with a lower risk of metastasis and higher disease-free survival times." (PMID 34830903, 2021). "We found that high immunohistochemical levels of Beclin-1 correlated with a lower risk of metastasis and higher disease-free survival times, indicating a positive prognostic role for Beclin-1 in uveal melanoma." (PMID 33330070, 2020). "There is evidence that Beclin-1 has a positive prognostic effect in uveal melanoma, with higher immunohistochemistry levels of the protein being associated with better outcomes in terms of metastasis risk and overall survival." (PMID 38467935, 2024). "In uveal melanoma patients, autophagy-associated proteins MAP1LC3A and BECN1 are commonly upregulated and are related to tumor development which resulted in poor prognosis." (PMID 34426753, 2021).
acute myeloid leukemia (5 papers, 2021 to 2025). Acute myeloid leukemia (AML) is a group of neoplasms arising from precursor cells committed to the myeloid cell-line differentiation. "Lower expression of key ATGs (BECN1, ATG3, ATG5, ATG4, ATG14) was shown in a large panel of primary acute myeloblastic leukemia (AML) patients as compared to normal granulocytes." (PMID 37887330, 2023).
endothelial dysfunction (5 papers, 2021 to 2025). In vascular diseases, endothelial dysfunction is a systemic pathological state of the endothelium (the inner lining of blood vessels) and can be broadly defined as an imbalance between vasodilating and vasoconstricting substances produced by (or acting on) the endothelium. "For example, aspirin inhibited autophagy by regulating beclin-1 phosphorylation through Vps15 scaffold, and reversed endothelial dysfunction induced by Estrogen." (PMID 35259050, 2022). "Aspirin suppressed autophagy by modulating beclin-1 phosphorylation via Vps15 scaffold and reversed estrogen-induced endothelial dysfunction." (PMID 35259050, 2022).
head and neck cancer (5 papers, 2021 to 2025). A primary or metastatic malignant neoplasm affecting the head and neck. "In certain tumors, including head and neck cancer, dysregulated autophagy is closely associated with cancer cell survival, migration, and drug resistance, suggesting that abnormalities in the ubiquitination status of Beclin 1 may significantly influence cancer cell fate." (PMID 40486910, 2025). "Specifically, the allelic deletion of the crucial autophagy protein Beclin 1 (also referred to as Atg6) is responsible for the development of head and neck cancer in mice." (PMID 39031216, 2024). "A recent study showed that poly(rC)-binding protein 1 repressed ferritinophagy-mediated ferroptosis through binding to CU-rich elements in 3′-UTRs of BECN1 mRNA in head and neck cancer." (PMID 37522124, 2023). "In head and neck cancer cells, knockdown of the cytosolic iron chaperone poly (rC)-binding protein 1 (PCBP1) increased BECN1 mRNA stability and inhibited xCT expression and viability, thereby promoting ferroptosis." (PMID 37745084, 2023). "In head and neck carcinoma, the activation of autophagy through upregulation of LC3B and BECN1 produces a tumor suppressive effect." (PMID 34573109, 2021).